MIF (macrophage migration inhibitory factor)
Diseases named in the same sentence as MIF in open-access papers (continued):
Sharing a sentence is not in itself a finding about the gene and the disease.
ovarian carcinoma (44 papers, 2007 to 2025). A malignant neoplasm originating from the surface ovarian epithelium. "MIF has been implicated in the angiogenic switch during progression of early cancers and plays a role in macrophage-induced ovarian cancer cell invasiveness." (PMID 31035430, 2019). "Furthermore, a proteomic analysis indicated the utility of MIF in diagnostic screening, and a multiplex test combining MIF with other biomarkers, including CA-125 and prolactin, demonstrated high sensitivity (95.3%) and specificity (99.4%) for ovarian cancer detection." (PMID 41159021, 2025). "Serum analysis from patients with newly diagnosed OC, showed significantly increased MIF levels in the cancer group compared to those in healthy age-matched controls, suggesting a possible link between abnormal MIF expression and ovarian cancer pathogenesis." (PMID 41159021, 2025). "Blocking MIF using anti-MIF antibodies resulted in enhanced lytic activity of NK cells against ovarian cancer cells from ascites." (PMID 41159021, 2025). "As a potential biomarker, MIF has emerged as a valuable tool in the prognosis and diagnosis of ovarian cancer." (PMID 41159021, 2025). "Clinically relevant doses of MIF significantly improve the efficacy of chemotherapy regimens for human ovarian carcinoma cells." (PMID 36984647, 2023). "Contributing to anti-inflammatory, and immune evasive phenotypes in malignant disease, MIF was also reported to be elevated in ovarian cancer cells." (PMID 36248860, 2022). "MIF is a key immunosuppressive cytokine produced by various cells and tissues that promote tumor progression mediated by macrophages in ovarian cancer and other cancer entities." (PMID 33819196, 2021). "More importantly, MIF has been found to have high circulating levels in various malignancies, including epithelial ovarian cancer." (PMID 33477343, 2021). "MIF is also highly expressed in patients with ovarian cancer, which is related to the development of ovarian cancer." (PMID 34485124, 2021). "Early detection of ovarian cancer can reduce mortality, MIF plays an important role in early detection of ovarian cancer." (PMID 34485124, 2021). "MIF overexpression in ovarian cancer cell lines also promotes immune evasion in NK cells; in this case by inducing the transcriptional downregulation of ovarian tumor target cell NKG2D that triggers NK-mediated tumor cell cytolysis." (PMID 33324425, 2020). "While OPN and MIF have previously been cited as potential biomarkers for ovarian cancer, in this study we have had the opportunity for the first time to evaluate OPN and MIF in large numbers of patients with early stage disease." (PMID 31035430, 2019). "In this study we have identified three biomarkers—OPN, MIF and anti-IL-8 AAb—that detect early stage ovarian cancers missed by CA125." (PMID 31035430, 2019). "The overexpression of MIF has been demonstrated in the progression of multiple cancers, such as ovarian cancer, hepatocellular carcinoma, gastric cancer, and other malignant cancers." (PMID 31293831, 2019). "Complementarity between CA125 and OPN, MIF and anti-IL-8 AAb was demonstrated by ROC analysis of both the discovery set and the validation sets of sera from patients with early stage ovarian cancer." (PMID 31035430, 2019). "We agree that osteopontin and possibly MIF deserve further evaluation as part of biomarker panels for detection of early stage ovarian cancer." (PMID 31540545, 2019). "For example, cancer cells from ovarian cancer ascites fluid release macrophage migration inhibitory factor (MIF), a chemokine that stimulates tumor-cell proliferation, migration, and metastasis." (PMID 30200478, 2018). "First, ovarian cancer cells release the pro-inflammatory cytokine macrophage migration inhibitory factor (MIF), which stimulates tumor cell proliferation, migration, and metastasis and promotes tumor angiogenesis." (PMID 28275576, 2017).
ovarian carcinoma (continued). "We furthermore analyzed ascites fluid from ovarian cancer patients by ELISA to determine the amount of oxMIF and total MIF." (PMID 27636991, 2016). "Enhanced expression of MIF has previously been reported in the serum of ovarian cancer patients and correlated with poor patient prognosis." (PMID 27470985, 2016). "Higher levels of serum macrophage migration inhibitory factor (MIF) were found in ovarian cancer patients’ blood (sensibility of 77,8% and specificity of 53,3%)." (PMID 19384429, 2007). "We demonstrate these effects by evaluating conditions of blood collection in one established and two novel ovarian cancer serum markers: CA 125, Prolactin, and Macrophage Migration Inhibitory Factor (MIF)." (PMID 18060075, 2007). "Studies have reported elevated levels of MIF in ovarian cancer (OC) cells, leading to the hypothesis that higher MIF levels may characterize patients with ovarian cancer." (PMID 41159021, 2025). "MIF involves in the development and progression of various types of cancer, such as gastric cancer, bladder cancer, ovarian cancer and esophageal cancer by interfering cell cycle, inhibiting anti-tumor immunity, promoting tumor cell proliferation and angiogenesis." (PMID 39891284, 2025). "Research reported high expression of MIF in malignant ascites, and in ovarian cancer cells." (PMID 41159021, 2025). "Furthermore, MIF is secreted in ascites, and its serum levels in patients with ovarian cancer correlate with a poor prognosis." (PMID 36352420, 2022). "MIF is known to be produced by ovarian cancer cells in an autocrine manner and may promote colonization of the peritoneum and neovascularization of tumor deposits by other cytokines, chemokines, and growth factors." (PMID 36352420, 2022). "We report the development of a blood test measuring four proteins (macrophage migration inhibitory factor, osteopontin, prolactin and cancer antigen 125), which can distinguish ovarian cancer samples, even early-stage disease, from healthy samples in the population tested." (PMID 33477343, 2021). "However, in recent years, more studies have focused on the relationship between MIF and early diagnosis of ovarian cancer." (PMID 34485124, 2021). "High expression of MIF is correlated with poor overall survival of ovarian cancer." (PMID 34109184, 2021). "Another study by Thorpe and colleagues investigated three protein biomarkers (Mucin-16, also known as CA-125), Prolactin (PRL) and Macrophage Migration Inhibitory Factor (MIF) in healthy women and women undergoing gynaecologic surgery in relation to ovarian cancer." (PMID 32867270, 2020). "Elevated MIF was detected in 21% of early stage and 39% of late stage ovarian cancers." (PMID 31035430, 2019). "Moreover, CA-125 with CA 19–9, EGFR, G-CSF, Eotaxin, IL-2R, cVCAM, MIF improved the sensitivity with 98.2 % and specificity of 98.7% in early stage detection of ovarian cancer." (PMID 31867451, 2019). "Elevated levels of MIF are found in ascites and in the circulation of ovarian cancer patients." (PMID 30274280, 2018). "Finally, also the pro-inflammatory cytokine macrophage migration inhibitory factor (MIF) has been shown to inhibit the NKG2D expression in peripheral blood (PB) NK cells derived from ovarian cancer patients." (PMID 24639677, 2014). "Dr Gil Mor’s group identified a panel of 6 biomarkers, CA-125, osteopontin (OPN), insulin-like growth factor 2 (IGF-II), macrophage migration inhibitory factor (MIF), leptin and prolactin, which demonstrated a sensitivity of 95.3% and a specificity of 99.4% for the detection of ovarian cancer." (PMID 24116163, 2013). "Additionally, TNF-α was reported to induce the secretion of MIF from dendritic cells and ovarian cancer cells." (PMID 21152395, 2010). "Therefore, our findings may be valuable not only for helping to explain the role of MIF in ovarian cancer but also for designing targeted therapies that act on specific molecular targets of cancer cells that may activate CAFs." (PMID 36352420, 2022).
ovarian carcinoma (continued). "Specifically, MIF reduces the expression of NKG2D, an activating receptor on NK cells, impairing their ability to lyse ovarian cancer cells." (PMID 41159021, 2025). "For example, macrophage migration inhibitory factor (MIF) can inhibit the activation of EGFR, while EGFR can promote the growth of various tumors and has been identified as a key therapeutic target of epithelial ovarian cancer." (PMID 37719881, 2023). "In this study we determine the value of combining macrophage migration inhibitory factor (MIF), osteopontin (OPN), and prolactin (PROL) with CA-125 in the detection of ovarian cancer serum samples from healthy controls." (PMID 33477343, 2021). "Our objective is to determine the combined utility of CA-125, MIF, OPN and PROL in distinguishing ovarian cancer serum samples from healthy controls and compare its usefulness to CA-125 alone as a single biomarker." (PMID 33477343, 2021). "Combining MIF, OPN, PROL, and CA-125 can better differentiate ovarian cancer from healthy controls compared to CA-125 alone." (PMID 33477343, 2021). "In both discovery and validation sets, a four-biomarker panel of osteopontin, macrophage migration inhibitory factor, IL-8 AAb and CA125 exhibited greater sensitivity than CA125 alone in detecting early stage ovarian cancer." (PMID 31035430, 2019). "Our study demonstrated that OPN, MIF and IL8 AAb can enhance the sensitivity of CA125 to distinguish ovarian cancer patients from health controls at high specificity." (PMID 31035430, 2019). "In another instance, a panel of six biomarkers consisting of CA-125, osteopontin, leptin, prolactin, MIF and IGF-II improved the sensitivity at 95.3 % and specificity at 99.4 % for ovarian cancer detection." (PMID 31867451, 2019). "Other factors linking inflammation and epithelial ovarian cancer, include serum amyloid A (SAA1/2) and macrophage migration inhibitory factors (MIF)." (PMID 30274280, 2018). "On the other hand, MIF overexpression was reported to facilitate immune evasion by downregulating NKG2D expression on tumor cells, a key receptor involved in triggering NK-mediated tumor cell cytolysis in ovarian cancer cell lines." (PMID 41159021, 2025). "Besides, MIF inhibits antitumor immunity through downregulating NKG2D on NK cells at the transcriptional level, in turn, impairing NK cells cytotoxicity towards ovarian cancer cells." (PMID 35842634, 2022). "A significant negative correlation between serum MIF and NK cells levels has recently been reported in ovarian cancer patients before and after chemotherapy, suggesting that MIF inhibits the production and activation of NK cells." (PMID 35842634, 2022). "MIF, as one of the biomarkers for early detection of ovarian cancer, combined with CA125, OPN and anti-IL-8 autoantibody can increase the detection rate of early ovarian cancer to 82%, which significantly improves the detection rate of early ovarian cancer." (PMID 34485124, 2021). "Eight immune factors (IFT57, MAL, ANXA4, SCRN1, LTBR, KIFAP3, HSPA5, and LTN1) were positively correlated with poor prognosis of ovarian cancer, whereas six immune factors (PSMB9, FOXJ1, CTSH, MIF, CTSD, and PSMB8) were negatively correlated with poor prognosis of ovarian cancer." (PMID 34109184, 2021). "Consequently, OPN, MIF and IL-8 autoantibodies can be used in combination with CA125 to distinguish ovarian cancer patients from healthy controls with high sensitivity." (PMID 31035430, 2019). "OPN, MIF, anti-IL-8 AAb and CA125 levels were measured in an independent validation set of sera from 71 patients with early stage ovarian cancer, 45 patients with late stage ovarian cancer and 131 healthy participants in the NROSS trial." (PMID 31035430, 2019).
ovarian carcinoma (continued). "Thus, the objective of this study is to assess the performance of the four top-performing markers, MIF, OPN, PROL and CA-125 in detecting ovarian cancer patients from healthy controls in a retrospective study comprised of patients with both early and late-stage ovarian cancer." (PMID 33477343, 2021). "Finally, MIF contributes to tumor immune escape by inhibiting CD8+ T lymphocyte and natural killer cell responses through the downregulation of the NKG2D receptor in ovarian cancer cells." (PMID 30634708, 2019). "The combination of the mentioned six biomarkers (MIF, OPN, CA125, IGF II, leptin and prolactin) has been shown to improve differentiation between disease free and ovarian cancer patients compared to CA125 alone in patients without a family history of OC." (PMID 29244844, 2017).
multiple sclerosis (41 papers, 2009 to 2025). A progressive autoimmune disorder affecting the central nervous system resulting in demyelination. "It has shown efficacy in a Phase II trial for multiple sclerosis, where high-expression MIF genotypes increase disease risk." (PMID 41159021, 2025). "Several studies have demonstrated that elevated MIF levels were associated with inflammatory neurological disorders such as neuron-Behcet's disease and different forms of multiple sclerosis." (PMID 19284533, 2009). "However, while MIF and D-DT appear to share similar pathogenic roles in multiple sclerosis, they seem to have diverging roles in other diseases, including systemic sclerosis." (PMID 36110852, 2022). "The anti-MIF activity of Ibudilast has propelled attention for the possible repurposing of this drug in immunoinflammatory pathologies where MIF is thought to be implicated, such as multiple sclerosis." (PMID 31752120, 2019). "Originally developed as a phosphodiesterase inhibitor, the small molecule inhibitor ibudilast was found to allosterically inhibit MIF and showed efficacy in a phase II clinical trial of multiple sclerosis patients." (PMID 40092999, 2025). "Patients with multiple sclerosis had an increase in the MIF-173 CC genotype and exhibited significantly lower age of disease onset compared with those with the MIF-173 CG and MIF-173 GG genotypes." (PMID 38178143, 2024). "MIF levels have been found to be highly expressed in human active multiple sclerosis lesions, and MIF plays an upstream mediating role in many neuroinflammations involving autoimmune." (PMID 36824264, 2023). "MIF is the subject of research in various neurological diseases such as multiple sclerosis, Alzheimer’s disease, and MDD." (PMID 36555097, 2022). "Proinflammatory cytokine macrophage migration inhibitory factor (MIF) is a multifunctional cytokine and has been found involved in many neurological diseases such as Alzheimer disease (AD), epilepsy, and multiple sclerosis." (PMID 32903462, 2020). "For example, the pleiotropic proinflammatory cytokine macrophage migration inhibitory factor (MIF) which activates the MEK/ERK pathway is upregulated and centrally implicated in the pathogenesis of both multiple sclerosis and rheumatoid arthritis." (PMID 32753665, 2020). "In inflammatory diseases, MIF -173 was found to be a disease severity marker for male multiple sclerosis patients, while the minor homozygous genotype for both the 974 CATT repeat and the -173G/C polymorphism were reported to protect female patients from major depressive disorder." (PMID 38476376, 2024). "In humans, increased expression of MIF has been linked to pathogenesis in inflammatory conditions across organ systems, including atherosclerosis, asthma, cystic fibrosis, IBD, nephrotic syndrome, multiple sclerosis, rheumatoid arthritis, and lupus." (PMID 32244916, 2020). "In this manner, MIF inhibition offers an alternative strategy for anti-inflammatory therapy in neuroinflammation such as multiple sclerosis and Guillain-Barré syndrome, although the effects of MIF on prescribed glucocorticoid analogues in patients require further consideration." (PMID 22973314, 2012). "Similar to our data in males and further female subgroups, two studies could also not find an association of the rs755622 genotypes with MIF serum levels in systemic sclerosis and multiple sclerosis patients." (PMID 36555097, 2022). "Pharmacologic inhibitors of host MIF and CD74 have been studied extensively and have already advanced into human trials for treatment of SLE, multiple sclerosis and multiple myeloma." (PMID 32244916, 2020). "For this purpose, we carried out a transcriptomic analysis of MIF, DDT, and their receptors and co-receptors in CIS patients with subsequent rapid development of Clinically Definite Multiple Sclerosis (CDMS)." (PMID 31581595, 2019).
multiple sclerosis (continued). "Furthermore, evidence for the role of MIF in the development, pathogenesis, and treatment of SLE, spondyloarthritis, juvenile idiopathic arthritis, granulomatosis with polyangiitis, Type 1 diabetes, multiple sclerosis, and autoimmune myocarditis have been reported." (PMID 40092999, 2025).